HMGB1 (high mobility group box 1)
Diseases named in the same sentence as HMGB1 in open-access papers (continued):
Sharing a sentence is not in itself a finding about the gene and the disease.
breast carcinoma (continued). "This study aimed to investigate the effects of cancer-associated fibroblasts on HMGB1 expression in breast cancer cells and its role in chemotherapeutic response." (PMID 25512109, 2014). "Evaluation of the prognostic significance of HMGB1 expression by Kaplan–Meier survival analysis using the GSE96058 dataset revealed the association of the increased HMGB1 expression with poorer overall survival in patients with breast cancer." (PMID 40389855, 2025). "Furthermore, resistance to adriamycin caused by HMGB1 has also been found in breast cancer and neuroblastoma." (PMID 38725632, 2024). "HMGB1 also induces breast cancer-associated bone pain via RAGE binding to sensory neurons." (PMID 39830522, 2024). "HMGB1 has recently been identified as a potential diagnostic biomarker for breast cancer because it may be involved in its development and progression of breast cancer." (PMID 37684327, 2023). "In vitro studies with an orthotopic mouse tumor, analysis of serum from breast cancer patients, and meta-analysis of human breast cancer patient data indicate that tumor-derived HMGB1 is closely associated with metastasis in triple-negative breast cancer patients." (PMID 36831371, 2023). "In breast cancer, HMGB1 translocation was demonstrated to be associated with pyroptosis." (PMID 36267972, 2022). "Interestingly, in addition to the typical characteristics, HMGB1 can also regulate the complications associated with breast cancer." (PMID 35637945, 2022). "For example, in breast cancer, one study showed that chemotherapy was associated with decreased serum HMGB1, which correlated with treatment efficacy, while a separate study demonstrated that complete loss of HMGB1 was linked to poor response." (PMID 36497086, 2022). "In breast cancer, the association between hypoxia and HMGB1 has also been confirmed." (PMID 35637945, 2022). "Subgroup analysis was also performed by the type of malignancy and ethnicity stratification in the current study, however, no obvious differences were found in the tumour risks in the HMGB1 rs1045411 polymorphism amongst the cancer types except for breast cancer and hepatocellular carcinoma." (PMID 33628090, 2021). "However, a separate study reported that complete loss of HMGB1 is linked to poor response in breast cancer." (PMID 34497771, 2021). "The present study aimed to investigate whether hypoxia‐responsive miR‐141–3p was implicated in the pathogenesis of breast cancer via mediating the high‐mobility group box protein 1 (HMGB1)/hypoxia‐inducible factor (HIF)‐1α signaling pathway." (PMID 32436353, 2020). "However, low nuclear HMGB1 expression can also be associated with shorter median survival time in pancreatic and with poor prognosis in breast cancer." (PMID 31379812, 2019). "Both TLR4, expressed on APC, and HMGB1 are required for ICD and for efficient immune stimulation as demonstrated in experiments neutralizing HMGB1 and in breast cancer patients having a loss-of-function TLR4 allele exhibiting reduced binding affinity for HMGB1." (PMID 29462947, 2018). "Anti-HMGB1 neutralizing antibody also significantly decreases the effect of released extracellular HMGB1 from cancer-associated fibroblasts or recombinant HMGB1 on doxorubicin (DOX) resistant breast cancer cells." (PMID 28969092, 2017). "A higher level of HMGB1 was associated with a poorer prognosis or more malignant phenotypes in multiple solid tumors, such as nasopharyngeal, lung, skin, hepatic, gastric, and prostate cancers, with the exception of breast cancer." (PMID 20846416, 2010). "For example, in breast cancer (BC) patients, HMGB1 expression serves as an effective indicator of the immunogenicity and efficacy of chemotherapeutic agents, and elevated levels of HMGB1 have been associated with improved clinical outcomes in patients receiving neoadjuvant chemotherapy." (PMID 40877572, 2025).
breast carcinoma (continued). "Within the MCF - 7 breast carcinoma cell line, HMGB1, which possesses the LXCXE sequence, enhances the transcriptional capacity of cell cycle protein A inhibition by interacting with the Rb gene, inducing cell arrest and death in the G1 phase." (PMID 40969278, 2025). "While HMGB1 dysfunction can contribute to tumorigenesis, intracellular HMGB1 in breast cancer can function as a tumor suppressor by inducing cell cycle arrest and apoptosis." (PMID 39782693, 2025). "In patients with breast cancer, high HMGB1 levels showed a significantly poorer overall survival rate than low HMGB1 levels." (PMID 40389855, 2025). "Next, we performed a Pearson correlation analysis between the estimated immune score and HMGB1 mRNA expression in the Clinical Proteomic Tumor Analysis Consortium (CPTAC) dataset to determine the immunologic relevance of HMGB1 expression in breast cancer." (PMID 40389855, 2025). "In breast cancer, HMGB1 depletion compromises DNA repair signaling by suppressing key kinases of the DNA damage response ATM and ATR, thereby attenuating strand break repair efficiency." (PMID 41465435, 2025). "In breast cancer, HMGB1 enhances tumor stem cell self‐renewal capacity and promotes tumorigenesis and metastasis by activating TLR2, inducing IκBα phosphorylation, stimulating IL‐6 and TGF‐β secretion, and activating STAT3 and Smad3 signaling pathways." (PMID 41354099, 2025). "HMGB1 enhances tamoxifen resistance in breast cancer cells by binding to TLR4 and activating the NF‐κB signaling pathway." (PMID 41354099, 2025). "This stromal-amplified HMGB1 secretion fosters doxorubicin resistance in breast cancer cells, an effect that can be reversed by HMGB1-neutralizing antibodies." (PMID 41465435, 2025). "In this study, Yang and colleagues also demonstrated that silencing CXCL1 or blocking IGF1R/STAT3 signaling disrupts this HMGB1–autophagy–MRPs axis and restores drug sensitivity in breast cancer." (PMID 41465435, 2025). "Noteworthy, HMGB1 elevated expression in breast cancer is associated with a poorer response, though it also predicts greater benefit from CDK4/6 inhibitors, establishing HMGB1 not only as a resistance target but also as a predictive biomarker." (PMID 41465435, 2025). "Within the TME, TLR4 recognizes HMGB1 to activate the MyD88/NF-κB pathway, enhancing breast cancer invasion and angiogenesis." (PMID 41488647, 2025). "HMGB1 (high mobility group box-1 protein) from breast cancer cells also triggers aerobic glycolysis in CAFs, further promoting metastasis." (PMID 40230452, 2025). "Recent studies have shown that HMGB1 promotes chemotherapy resistance in breast cancer and esophageal cancer through HMGB1-mediated autophagy." (PMID 41164196, 2025). "Specifically, HMGB1 secreted by breast cancer cells promotes fibroblast activation via the RAGE/aerobic glycolysis pathway, and these activated fibroblasts subsequently enhance breast cancer cell metastasis by increasing lactate production." (PMID 40877572, 2025). "Our findings demonstrate a significant positive correlation between HMGB1 and PD-L1 expression in breast cancer patient data, cellular models, and animal experiments." (PMID 40389855, 2025). "Co-treatment with 1.7 mM metformin resulted in a reduction in colony size comparable to the control, indicating that metformin effectively counteracts HMGB1-driven cell proliferation in breast cancer cells." (PMID 40277915, 2025). "This study will help identify the potential therapeutic strategies targeting the nucleo-cytoplasmic translocation of HMGB1 in breast cancer." (PMID 40389855, 2025). "In support with this findings, ferroptosis inducers activate a prognostically adverse gene signature that includes HMGB1, linking its release to pathways of extracellular matrix remodeling and therapy resistance in aggressive breast cancer subtypes." (PMID 41465435, 2025). "In this study, we aimed to investigate the effects of intracellular HMGB1 on PD-L1 expression in breast cancer cells." (PMID 40389855, 2025).
breast carcinoma (continued). "The binding of extracellular HMGB1 to TLR2/4 activates MyD88‐dependent NF‐κB/STAT3 signaling in breast cancer cells, driving epithelial‒mesenchymal transition and chemoresistance, while simultaneously polarizing TAMs toward the M2 phenotype." (PMID 40727252, 2025). "Pharmacological inhibition of HMGB1 by CDK4/6 inhibitors has been also shown to present a powerful tool to overcome breast cancer resistance to tamoxifen by disrupting the TLR4-NF-κB pathway." (PMID 41465435, 2025). "HMGB1 expression is ubiquitously upregulated in various tumors, including breast cancer, lung cancer, and hepatocellular carcinoma." (PMID 41164196, 2025). "Multiple microRNAs, miR-142-3p, miR-34a, miR-129-5p, and miR-451, directly target HMGB1 to restore caspase activation and suppress autophagy in doxorubicin-resistant breast cancer, AML, retinoblastoma, and pediatric AML." (PMID 41465435, 2025). "Further experiments have shown that HMGB1 secretion in breast cancer cells promotes fibroblast activation, which, through RAGE, upregulates aerobic glycolysis and promotes the metastasis of breast cancer cells." (PMID 38529373, 2024). "In pancreatic cancer and human breast cancer, the HMGB1/RAGE axis controls cancer cell proliferation through the NF-κB signaling pathway." (PMID 38529373, 2024). "The invasion assay was performed on MDA-MB-231 and MCF-7, the two breast-cancer cell lines that differ in their metastatic properties, and for their potential to maintain HMGB1 in the reduced form." (PMID 38803493, 2024). "It was also shown that HMGB1 was involved with telomere homeostasis and prevented DNA damage induced by radiation in human breast cancer cells." (PMID 38273318, 2024). "Among these, miR-142-3p, which regulates HMGB1 formation, has been shown to fulfill an important immunomodulatory role in various cancers, such as breast cancer, lung cancer, colorectal cancer and gastric cancer." (PMID 39916954, 2024). "Its overexpression suppresses the migration and proliferation of breast cancer cells by targeting HMGB1." (PMID 39759512, 2024). "Previous studies demonstrated that CXCL1 induced autophagy-mediated chemoresistance in breast cancer cells by modulating HMGB1." (PMID 39394189, 2024). "The HMGB1/RAGE axis is involved in the metastasis of breast cancer, chondrosarcoma, and prostate cancer through the PI3K-AKT-mTOR signaling pathway, respectively." (PMID 38529373, 2024). "Another study showed that HMGB1-RAGE through PI3K/AKT signaling promotes not only breast cancer cell invasion but also PD-L1 expression which leads to the destruction of the effector T cells." (PMID 38469295, 2024). "In gastric cancer, prostate cancer, rhabdomyosarcoma, breast cancer, and hypopharyngeal cancer, the HMGB1/RAGE axis is involved in the migration, invasion, and EMT of these cancers." (PMID 38529373, 2024). "The dual anti-tumor and pro-tumor biological functions of HMGB1 make its precise role in breast cancer progression quite elusive." (PMID 39830522, 2024). "Clinical investigation also revealed that CXCL1 was an independent risk factor for breast cancer prognosis and positively correlated with IGF1R and HMGB1 expression." (PMID 39394189, 2024). "A clinical study focusing on basal-like breast cancer cells reported the release of high levels of HMGB1." (PMID 38725632, 2024). "Two anti-cancer drugs, quercetin and lucidone A, inhibit the HMGB1/RAGE axis to promote apoptosis in breast cancer and pancreatic cancer, respectively." (PMID 38529373, 2024). "The secretion of HMGB1 in breast cancer cells is positively correlated with their metastatic potential." (PMID 38529373, 2024). "Studies reported to date have correlated HMGB1 upregulation with the onset and progression of melanoma, colon cancer, breast cancer, and pancreatic cancer, chiefly pointing towards the role of HMGB1 in augmenting neo-angiogenesis in cancerous tumor." (PMID 39682695, 2024).
breast carcinoma (continued). "Meanwhile, CAF-derived HMGB1 was further confirmed to stimulate autophagy through MEK/ERK signaling in ERα-positive breast cancer cells, thus promoting tamoxifen resistance in cancer cells." (PMID 38649701, 2024). "In particular, overexpression of HMGB1 can restore the migration ability of breast cancer cells, which is inhibited by silencing of the hematological and neurological expressed 1-like (HN1L) gene." (PMID 38725632, 2024). "Clinically, CXCL1 was shown to be an independent predictor of poor prognosis and to be positively correlated with IGF1R/STAT3/HMGB1 expression in breast cancer." (PMID 39394189, 2024). "Overexpression of HMGB1 has been demonstrated in numerous types of cancer, including breast cancer, colorectal cancer, hepatocellular carcinoma and lung cancer." (PMID 37932766, 2023). "HMGB1 is positively related to autophagy level, NFκB/p65 activity, and doxorubicin-resistance in breast cancer cells." (PMID 37190065, 2023). "As a member of the high mobility group protein superfamily, HMGB1 has secretory and intracellular activity and participates in breast cancer tumorigenesis." (PMID 37190065, 2023). "Fibroblasts that promote tumor cell migration and invasiveness are also activated by HMGB1 released by a human breast cancer cell line as shown in a mouse xenograft setting." (PMID 36831371, 2023). "Using a three-dimensional in vitro gel system, HMGB1-treated human breast cancer cells gained enhanced migration ability and increased PD-L1 expression." (PMID 36831371, 2023). "In vitro and in vivo studies of breast-cancer-induced mouse MDSCs using inhibitors of autophagy and HMGB1 demonstrated that HMGB1 promotes MDSC survival by driving the cells into an autophagic state." (PMID 36831371, 2023). "The role of HMGB1 in the cytoplasm is associated with BECN1-mediated autophagy, metastasis, and chemo- and radiotherapy resistance in breast cancer." (PMID 37190065, 2023). "It has been shown that autophagic CAFs secreted HMGB1, activated Toll-like receptor-4 (TLR4, the receptor of HMGB1 found in luminal breast cancer cells), and acted on the number of cancer stem cells." (PMID 38234683, 2023). "In particular, the doxorubicin-induced immunogenic cell death releases TLR2-activating DAMPs, such as HMGB1, able to protects breast cancer cells from chemotherapy and promotes metastasis formation." (PMID 37822929, 2023). "The recombinant human milk peptide lactaptin RL2 induced calreticulin exposure, ATP and HMGB1 release in breast cancer cells and promoted the phagocytosis of dying-cancer cells by macrophages." (PMID 38077402, 2023). "The silencing of HMGB1 also reduces radiotherapy resistance in breast cancer, which is known to be related to the diminished autophagic activity." (PMID 37190065, 2023). "DAMPs such as HMGB1 and serum amyloid A 1 protein, secreted by breast cancer cells and elevated in the plasma and tumor biopsies from patients with advanced triple-negative breast tumors, induce an immunosuppressive response in neutrophils via TLR2." (PMID 38203626, 2023). "Defining the mechanisms of HMGB1 on regulating breast cancer development and progression will facilitate the application of HMGB1 as a therapeutic target for breast cancer." (PMID 35637945, 2022). "In short, downregulation of HMGB1 disrupts telomere homeostasis, inhibits DNA damage repair and enhances radiosensitivity in human breast cancer cells." (PMID 35637945, 2022). "The ability of HMGB1 to enhance the radiosensitivity of breast cancer cells is generally considered to be largely correlated to its immunogenic effects." (PMID 35637945, 2022). "Taken together, the data available in the literature along with the data reported herein support the pre-clinical studies to confirm HMGB1-RAGE interaction promoted breast cancer cell invasion via the PD-L1-mediated PI3K/AKT pathway." (PMID 35610613, 2022).
breast carcinoma (continued). "Taken all together, these data suggest that the HMGB1-RAGE-mediated PI3K/AKT pathway led to mediate PD-L1 expression in breast cancer cells." (PMID 35610613, 2022). "These functions determine the strategies for the development of chemotherapy, radiotherapy, immunotherapy and combination therapies by targeting HMGB1 in breast cancer." (PMID 35637945, 2022). "Various reports have shown that HMGB1 expression is significantly upregulated in breast cancer, gastric cancer, lung cancer and other cancers and downregulated in pancreatic cancer." (PMID 35354479, 2022). "In other words, the combined analysis of HMGB1 and autophagy levels is valuable for predicting breast cancer prognosis." (PMID 35637945, 2022). "The pro- and anti-tumor activity of HMGB1 have been reported on its carcinogenicity in breast cancer." (PMID 35637945, 2022). "Particularly, these miRNAs are generally shown to reverse HMGB1-induced resistance to chemotherapy or radiotherapy 65-67, 94, which provide new strategies for breast cancer therapy targeting HMGB1." (PMID 35637945, 2022). "The PI3K/AKT pathway has been reported to be involved in HMGB1 activation in lung cancer, breast cancer, and cutaneous squamous cell carcinoma." (PMID 35610613, 2022). "HMGB1 overexpression was confirmed in melanoma, colon cancer, prostate cancer, pancreatic cancer, and breast cancer." (PMID 35620407, 2022). "High-mobility group box 1 (HMGB1) is increased in breast cancer cells as the result of exposure to the secreted substances from cancer-associated fibroblasts and plays a crucial role in cancer progression and drug resistance." (PMID 35610613, 2022). "The profound impact of HMGB1 on the TME allows the combination of HMGB1 and other immune cells to be a new target for breast cancer prevention and treatment." (PMID 35637945, 2022). "For example, HMGB1 can regulate HIF-1α expression in breast cancer cells through the PI3K/AKT signaling pathway." (PMID 35637945, 2022). "The significant changes of phosphorylation are consistent with the expression level of HMGB1 total protein between normal tissue and primary tissue for breast cancer, clear cell RCC and UCEC." (PMID 35765707, 2022). "The PI3K/AKT dependent signaling pathway was suppressed by HMGB1, silenced in MCF-7 breast cancer cells and caused cancer cells to have less aggressive phenotypic characteristics including migration, invasion, and angiogenesis." (PMID 35610613, 2022). "Abnormal HMGB1 levels are frequently manifested in various malignant diseases, including breast cancer." (PMID 35637945, 2022). "The potential of the attenuation of the HMGB1-RAGE-dependent PI3K/AKT pathway in mediating PD-L1 expression is proposed to both inhibit HMGB1-induced breast cancer aggressiveness and T cell function attenuation." (PMID 35610613, 2022). "Collectively, these findings indicate that HMGB1-RAGE through PI3K/AKT signaling promotes not only breast cancer cell invasion but also PD-L1 expression which leads to the destruction of the effector T cells." (PMID 35610613, 2022). "Researchers showed that P2Et, an extract of Caesalpinia Spinosa, induces the release of HMGB1 and has synergistic effects with anthracycline-type chemotherapeutic agents in animal models of breast cancer." (PMID 35637945, 2022). "The role of HMGB1 on cell proliferation in breast cancer cells was investigated by 3-D tumor spheroid-based assays." (PMID 35610613, 2022). "Altogether, the expression pattern of HMGB1 can be applied to the assessment of prognosis, chemotherapy efficacy and immune infiltration of breast cancer, which provides valuable clinical evidence for breast cancer treatment strategies targeting HMGB1." (PMID 35637945, 2022). "The ability of HMGB1-mediated autophagy to confer chemoresistance of breast cancer cells has been confirmed in various conventional chemotherapeutic drug trials." (PMID 35637945, 2022).